TRGV11 (T cell receptor gamma variable 11 (non-functional))
Description:
Probable non-functional open reading frame (ORF) of V region of the variable domain of T cell receptor (TR) gamma chain. Non-functional ORF generally cannot participate in the synthesis of a productive T cell receptor (TR) chain due to altered V-(D)-J or switch recombination and/or splicing site (at mRNA level) and/or conserved amino acid change (protein level). Gamma-delta TRs recognize a variety of self and foreign non-peptide antigens frequently expressed at the epithelial boundaries between the host and external environment, including endogenous lipids presented by MH-like protein CD1D and phosphoantigens presented by butyrophilin-like molecule BTN3A1. Upon antigen recognition induces rapid, innate-like immune responses involved in pathogen clearance and tissue repair. Binding of gamma-delta TR complex to antigen triggers phosphorylation of immunoreceptor tyrosine-based activation motifs (ITAMs) in the CD3 chains by the LCK and FYN kinases, allowing the recruitment, phosphorylation, and activation of ZAP70 that facilitates phosphorylation of the scaffolding proteins LCP2 and LAT. This lead to the formation of a supramolecular signalosome that recruits the phospholipase PLCG1, resulting in calcium mobilization and ERK activation, ultimately leading to T cell expansion and differentiation into effector cells. Gamma-delta TRs are produced through somatic rearrangement of a limited repertoire of variable (V), diversity (D), and joining (J) genes. The potential diversity of gamma-delta TRs is conferred by the unique ability to rearrange (D) genes in tandem and to utilize all three reading frames. The combinatorial diversity is considerably increased by the sequence exonuclease trimming and random nucleotide (N) region additions which occur during the V-(D)-J rearrangements.
Synonyms: V4P; TCRGV11
Gene: T-cell receptor variable (V) gene on chromosome 7 (38,291,616 to 38,292,078, reverse strand). Ensembl gene ENSG00000211693.
Subcellular location: Cell membrane
Gene Ontology:
Cellular component: plasma membrane
Homologues: Orthologues: mouse Trgv4 (50% identical). Paralogues in human: TRGV10 (43% identical), TRGV9 (29% identical), TRGV1 (25% identical), TRGV5 (25% identical), TRGV3 (24% identical), TRGV4 (24% identical), TRGV8 (24% identical), TRGV2 (24% identical).
Diseases named in the same sentence as TRGV11 in open-access papers:
TRGV11 is named in the same sentence as 2 diseases in open-access papers, as found by Europe PMC text mining. Sharing a sentence is not in itself a finding about the gene and the disease.
TRGV11 shares sentences with these, for which no sentence is quoted: prostate tumors (1 paper); tumor (1).